DHODH (dihydroorotate dehydrogenase (quinone))
Diseases named in the same sentence as DHODH in open-access papers (continued):
Sharing a sentence is not in itself a finding about the gene and the disease.
neuroblastoma (continued). "All the three neuroblastoma cell lines reduced DHODH protein expression significantly after leflunomide incubation." (PMID 23977077, 2013). "Moreover, both wound healing and transwell migration assays showed that DHODH inhibition impaired neuroblastoma cell migration." (PMID 40513779, 2025). "•TMT proteomics shows DHODH inhibition rewires lipid metabolism in neuroblastoma." (PMID 40513779, 2025). "This suggests that lipid metabolism may be a key mechanism through which Regorafenib induces cell death in neuroblastoma by disrupting DHODH activity." (PMID 40513779, 2025). "Similarly, in neuroblastoma, inhibition of DHODH reprograms lipid metabolism through the mevalonate pathway, thereby promoting ferroptosis sensitivity and revealing a novel therapeutic vulnerability." (PMID 41369379, 2025). "Together, these results highlight the crucial role of DHODH in neuroblastoma progression and suggest that targeting DHODH could be a promising therapeutic strategy." (PMID 40513779, 2025). "The knockdown significantly reduced neuroblastoma cell growth and clonogenicity, an effect that was rescued by uridine (the end product of pyrimidine biosynthesis) and orotate (the product catalyzed by DHODH)." (PMID 40513779, 2025). "Despite its established role in cancer, the precise mechanisms by which DHODH influences neuroblastoma remain unclear." (PMID 40513779, 2025). "GO enrichment analysis of differentially expressed proteins suggested that Regorafenib may induce ferroptosis in neuroblastoma cells by inhibiting DHODH and disrupting the mevalonate pathway." (PMID 40513779, 2025). "Furthermore, the neuroblastoma study showed that DHODH blockage in combination with temozolomide (an alkylating agent) can lead to cure in a murine model." (PMID 38332874, 2024). "DHODH is an independent unfavorable prognostic marker in neuroblastoma." (PMID 35943801, 2022). "DHODH inhibition preferentially targets the neuroblastoma ADRN cell state." (PMID 35943801, 2022). "Neuroblastoma cells accumulate nucleotide metabolites and express high levels of DHODH." (PMID 35943801, 2022). "Taken together, these results may indicate that MYCN-driven neuroblastoma cells are less capable of pyrimidine salvage and more dependent on de novo pyrimidine biosynthesis via DHODH." (PMID 35943801, 2022). "DHODH inhibition is an effective therapy in preclinical models of neuroblastoma." (PMID 35943801, 2022). "We also observed that DHODH was commonly expressed in neuroblastoma." (PMID 23977077, 2013). "In this study, we showed that DHODH was commonly expressed in neuroblastoma." (PMID 23977077, 2013). "It means that the DHODH pathway is activated in neuroblastoma cells." (PMID 23977077, 2013). "We found that DHODH was common expressed in all three neuroblastoma cell lines." (PMID 23977077, 2013). "In our future study, we will focus on the DHODH function in neuroblastoma." (PMID 23977077, 2013). "Thus, we propose that Regorafenib may induce ferroptosis in neuroblastoma by disrupting DHODH activity and downregulating key proteins in the mevalonate pathway." (PMID 40513779, 2025). "Our findings underscore the importance of further investigating the role of the oxoacid metabolic process in neuroblastoma and suggest that targeting DHODH may present a promising approach for disrupting the metabolic networks that sustain cancer cell viability and progression." (PMID 40513779, 2025). "Moreover, in SK-N-AS cells (high MES score), we observed a plateau effect where increasing doses of brequinar did not further decrease cell viability, suggesting that neuroblastoma cells with a predominantly MES phenotype are less dependent on DHODH and more resistant to its inhibition." (PMID 35943801, 2022). "We next examined whether DHODH dependency correlates with MYCN dependency in neuroblastoma." (PMID 35943801, 2022). "Consequently, we next sought to explore the clinical relevance of DHODH in neuroblastoma." (PMID 35943801, 2022).
neuroblastoma (continued). "Quantitative TMT-based proteomic analysis revealed that DHODH inhibition by Regorafenib suppresses the mevalonate pathway, disrupts lipid droplet formation, and induces nuclear translocation of SQLE in neuroblastoma cells." (PMID 40513779, 2025). "This strong intercorrelation between CAD, DHODH, and UMPS was also evident in the subset of neuroblastoma cell lines." (PMID 35943801, 2022). "Our study highlights the critical role of DHODH, an enzyme essential for the de novo pyrimidine synthesis pathway, as a key non-oncogene dependency in neuroblastoma." (PMID 40513779, 2025). "The effect of DHODH inhibition on tumor cell growth was evaluated in a panel of neuroblastoma cell lines and a nonmalignant fibroblast cell line." (PMID 35943801, 2022). "We demonstrated that the ADRN neuroblastoma cells were more sensitive to DHODH inhibition in comparison with their MES counterparts, further substantiating our observation that the MES cell state is more resistant to DHODH inhibition." (PMID 35943801, 2022). "However, none of the existing FDA-approved DHODH inhibitors have shown effective inhibition of neuroblastoma cell growth." (PMID 40513779, 2025). "Regorafenib is a multi-kinase inhibitor that targets VEGFRs, PDGFR, RET, RAF kinases, and other signaling molecules, suggesting that its impact on neuroblastoma cells may not be solely due to DHODH inhibition." (PMID 40513779, 2025). "However, in contrast to the combination of BRQ and dipyridamole, DHODH inhibition with BRQ did not cause the suppression of proliferation and tumorigenicity of neuroblastoma cell lines when subjected to physiological uridine levels demonstrating again the need for co-targeting pyrimidine salvage." (PMID 35203388, 2022). "Teriflunomide and leflunomide, inhibitor of DHODH a key enzyme in nucleotide synthesis, have antiproliferative effects in NSCLC, myeloma and neuroblastoma but has not yet been approved by FDA for clinical use." (PMID 36618350, 2022).
viral infections (12 papers, 2020 to 2023). "An additional antiviral effect associated with DHODH inhibition is the anti-inflammatory activity triggered by the reduction in pathogenic cytokines usually overexpressed in severe virus infections." (PMID 36014049, 2022). "In virus infections, their diverse properties have been considered responsible for the antiviral activity of DHODH inhibitors." (PMID 36014049, 2022). "The data above refresh DHODH as an attractive host target in treating viral diseases with equivalent efficacy to DAA drug and is more advantageous when facing DAA-drug-resistant viruses." (PMID 32754890, 2020). "Similarly, DHODH inhibitors have been utilized in viral infection models to stimulate interferon-mediated signaling mechanisms and an anti-viral response." (PMID 37475852, 2023). "Whether ferroptosis is involved in the multifaceted activities of DHODH inhibitors remains an open question; nevertheless, targeting DHODH may have promise as a novel therapeutic approach for cancer and certain viral infections." (PMID 37735472, 2023). "Our observations prompt questions of whether the increased cell death is a result of DHODH inhibition in E. huxleyi or non-DHODH-related cytotoxic effects of brequinar that synergize with the stress of viral infection." (PMID 37869665, 2023). "It would therefore be of interest to determine if HHQ could inhibit E. huxleyi PARP, thereby averting the PCD response that would typically be realized by DHODH inhibition and / or viral infection." (PMID 37869665, 2023). "Interestingly, inhibiting DHODH not only blocks de novo pyrimidine synthesis, but also augments interferon response against viral infection." (PMID 38257735, 2023). "Although the DHODH inhibitors leflunomide and teriflunomide are clinically available, they are currently only approved for autoimmune disease treatment, while other application in treating viral infection is still under investigation." (PMID 38257735, 2023). "This could be a beneficial feature of DHODH inhibition in viral infection, since patients may rather initiate antiviral treatment in a later phase, when the symptoms have manifested, than at early time points." (PMID 33291455, 2020). "In recent years, there have been reported that DHODH inhibitors IMU-838 (synonym of Vi) and teriflunomide could antagonize viral infections such as SARS-CoV-2 and West Nile virus, respectively." (PMID 38124181, 2023).
COVID-19 (9 papers, 2020 to 2024). A disease caused by infection with severe acute respiratory syndrome coronavirus 2. "In summary, we propose that the combination of DHODH inhibitors with NHC targets and abolishes virus replication, whereas DHODH inhibition may also ameliorate COVID-19-associated immunopathology." (PMID 35492218, 2022). "In conclusion, combining molnupiravir and a DHODH inhibitor proved effective in the hamster model of COVID-19." (PMID 35492218, 2022). "It remains to be determined how DHODH inhibitors will affect the T cell response in the context of COVID-19." (PMID 35492218, 2022). "With regard to the use of DHODH inhibitors for the treatment of COVID-19, it is also relevant to mention that diabetes is a clear risk factor." (PMID 34113829, 2021). "Recent studies have indicated that a DHODH blockade can be effective for the treatment of COVID-19." (PMID 37744270, 2023). "Combining molnupiravir with DHODH inhibitors may thus improve available therapy options for COVID-19." (PMID 35492218, 2022). "Moreover, inhibitors of DHODH, including leflunomide, are also considered to combat RNA virus infections and have now entered clinical trials for coronavirus disease 2019 (COVID-19) (clinicaltrials.gov)." (PMID 34113829, 2021). "BRQ is the most potent human DHODH inhibitor (IC50 = 1.8 nM), with known potential to specifically decrease the proliferation of glioblastoma cells; and it is in clinical trials for application against COVID-19 and AML (go.drugbank.com/drugs/DB03523)." (PMID 36814599, 2023). "How FSP1pathway relates specifically to COVID-19 pathophysiology has not been investigated yet, conversely a very recent review reported the outcomes of two preliminary in-vitro studies where DHODH inhibitors halted SARS-CoV-2 replication." (PMID 35340277, 2022). "One DHODH inhibitor, IMU-838 (Vidofludimus calcium), was further clinically evaluated for COVID-19 therapy in hospitalized patients and was found effective according to secondary criteria, e.g. time to clinical improvement or viral burden (CALVID-1, trial identifier NCT04379271; NCT04516915)." (PMID 35492218, 2022). "Moreover, DHODH, HDAC, and JAK2 are considered noteworthy targets in COVID-19-related research." (PMID 39130417, 2024). "Overall, IMU-838 is a potent DHODH inhibitor nominated as a highly interesting developmental candidate for the treatment of specific diseases including COVID-19, as particularly focused by the CALVID-1 trial (NCT04379271) intended for the clinical benefit of COVID-19 patients." (PMID 33291455, 2020).
glioblastoma (9 papers, 2020 to 2025). The most malignant astrocytic tumor (WHO grade IV). "In glioblastoma, DHODH stabilization by PRR11 was found to maintain mitochondrial function and ferroptosis resistance, further enhancing temozolomide resistance." (PMID 41369379, 2025). "For instance, in glioblastoma models resistant to temozolomide, DHODH inhibition disrupts mitochondrial antioxidant defenses, sensitizing tumors to ferroptosis and improving survival outcomes." (PMID 41369379, 2025). "With the renewed recognition of DHODH’s role in ferroptosis, brequinar or its liposome has resurfaced as a promising candidate for combination therapy in resistant tumors such as glioblastoma, colorectal cancer, and hepatocellular carcinoma." (PMID 41369379, 2025). "High DHODH levels correlate with poor clinical outcomes in colorectal cancer, hepatocellular carcinoma, glioblastoma, and triple-negative breast cancer." (PMID 41369379, 2025). "Glioblastomas and hepatocellular carcinomas with high metabolic stress adapt by upregulating DHODH, and inhibition of this enzyme restores sensitivity to chemotherapeutics such as temozolomide and platinum drugs." (PMID 41369379, 2025). "Inhibiting DHODH can also deplete the cellular pyrimidine nucleotide supply to suppress the survival, proliferation, and tumorigenesis of glioblastoma stem cells." (PMID 38796629, 2024). "Higher expression of pyrimidine synthesis genes including DHODH portends poor prognosis of patients with glioblastoma." (PMID 33971967, 2021). "Pharmacological inhibition of DHODH with the specific inhibitors brequinar or ML390 effectively depleted the pool of pyrimidines in glioblastoma cells grown in vitro and in vivo and impaired rDNA transcription, leading to nucleolar stress." (PMID 33201894, 2020). "As others previously demonstrated, DHODH inhibition leads to a decrease in proliferation of glioblastoma cells." (PMID 33201894, 2020). "Nonetheless, here, we show that glioblastoma TMZ-resistant cells are still dependent on functional DHODH to proliferate, suggesting that targeting DHODH can provide a unique therapeutic intervention route to treat TMZ-resistant tumors." (PMID 33201894, 2020). "Altogether, these results indicate that uridine specifically rescues the inhibition of DHODH and the growth of glioblastoma cells." (PMID 33201894, 2020). "Similarly, metal–phenolic network nanoparticles carrying DHODH inhibitors and temozolomide were shown to overcome drug resistance in glioblastoma by disrupting multiple ferroptosis defense arms." (PMID 41369379, 2025). "Indeed, inhibition of the dihydroorotate dehydrogenase (DHODH) enzyme downstream of CAD suppressed growth of glioblastoma, triple negative breast cancer, and colon cancer, demonstrating the importance of pyrimidine synthesis in tumor growth." (PMID 37658191, 2023). "Given the effects of brequinar and ML390 on the production of 47S pre-rRNA, we asked whether prolonged inhibition of DHODH affects the proliferation of glioblastoma cells." (PMID 33201894, 2020). "While inhibition of DHODH causes a decrease in rRNA production in glioblastoma cells, it does not affect ACTIN abundance at short incubation periods." (PMID 33201894, 2020). "Moreover, DHODH inhibition decreased the proliferation of glioblastoma cells, including temozolomide-resistant cells." (PMID 33201894, 2020). "In summary, our data show that the inhibition of the de novo pyrimidine biosynthesis by targeting the enzymatic activity of DHODH leads to efficient inhibition of rRNA production and nucleolar stress and therefore, decreases proliferation specifically in glioblastoma cells." (PMID 33201894, 2020).
glioblastoma (continued). "Therefore, we conclude that DHODH inhibition specifically limits the production of pre-rRNA and thus affects the viability of glioblastoma cells." (PMID 33201894, 2020). "Therefore, we examined apoptosis by measuring cleaved caspase 3 to define whether the decrease in cell number upon DHODH inhibition in glioblastoma cells was also due to increase cell death." (PMID 33201894, 2020). "Importantly, the inhibition of the de novo pyrimidine biosynthesis with brequinar did not alter UBF distribution or the nucleolar morphology of the non-transformed ARPE cells, indicating that only the transformed glioblastoma cells suffer nucleolar stress upon DHODH inhibition." (PMID 33201894, 2020). "To test whether addition of exogenous uridine can rescue the effects of inhibiting DHODH in proliferation, we first determined the highest uridine concentrations tolerated by glioblastoma cells without causing off-target effects and cell death." (PMID 33201894, 2020). "In glioblastoma, PRR11–DHODH interactions contribute to temozolomide resistance, while DHODH inhibition sensitizes tumors to ferroptosis and restores drug response." (PMID 41369379, 2025). "For example, DHODH is a downstream regulator of PRR11, which maintaining DHODH protein stability by inhibiting the binding between E3 ubiquitin ligase HERC4 and DHODH in glioblastoma." (PMID 40715045, 2025). "Western blot analysis indicated that DHODH and UMPS protein levels were higher in the glioblastoma cells LN229, GBM9, and SF188 in comparison to normal human p14ARF-/- immortalized astrocytes, which are non-transformed differentiated glial cells." (PMID 33201894, 2020). "By analyzing The Cancer Genome Atlas (TCGA) and the Chinese Glioma Genome Atlas (CGGA), we found that the mRNA levels of the enzymes in the de novo pyrimidine pathway, DHODH and UMPS, were elevated in high-grade glioma (IV/glioblastoma) patient samples." (PMID 33201894, 2020). "In this study, we show that enzymes necessary for the de novo biosynthesis of pyrimidines, DHODH and UMPS, are elevated in high grade gliomas and in glioblastoma cell lines." (PMID 33201894, 2020). "Moreover, our lab recently discovered that the transcription factor aryl hydrocarbon receptor (AHR), which is necessary for glioblastoma growth, mediates the expression of DHODH and UMPS in MYC-overexpressing fibroblasts and glioblastoma cells." (PMID 33201894, 2020). "Consequently, the impairment of the pre-rRNA synthesis upon DHODH inhibition leads to nucleolar stress specifically in glioblastoma cells but not in non-transformed cells." (PMID 33201894, 2020). "Thus, we report here that glioblastoma cells, including TMZ-resistant cells, are specifically vulnerable to pharmacologic inhibition of the enzyme DHODH and that inhibiting de novo pyrimidine biosynthesis effectively decreases the production of rRNA in glioblastoma cells." (PMID 33201894, 2020). "This suggest that the inhibition of DHODH can be used as a sequential step after TMZ treatment and not necessarily in combination with it, indicating that it could become an alternative approach to treat glioblastoma patients that develop TMZ resistance." (PMID 33201894, 2020).